TFEB (transcription factor EB)
Diseases named in the same sentence as TFEB in open-access papers (continued):
Sharing a sentence is not in itself a finding about the gene and the disease.
pancreatitis (5 papers, 2020 to 2026). Inflammation of the pancreas. "TFEB, a master regulator of lysosomal biogenesis, has been confirmed to be associated with the pathogenesis of experimental pancreatitis." (PMID 36793898, 2023). "It was recently demonstrated that in an experimental pancreatitis mouse model, cerulein decreased pancreatic TFEB proteins and TFEB-mediated lysosomal biogenesis, causing decreased lysosome numbers and insufficient autophagic flux." (PMID 32349207, 2020). "To determine whether decreased acinar cell TFEB would play a causal role in alcohol-induced pancreatitis, we generated inducible acinar cell–specific TFEB knockout (KO) mice and subjected these mice and their matched wild-type (WT) mice to Gao-binge alcohol model." (PMID 31987928, 2020). "The overexpression of TFEB increases the autophagy levels in major organs and protects against LPS induce acute lung injury or inflammatory liver injury and pancreatitis." (PMID 34899355, 2021). "Collectively, these data indicate that TFEB-mediated lysosomal biogenesis is impaired in alcohol-induced pancreatitis in mice." (PMID 31987928, 2020). "Together, these recent findings strongly indicate that impaired TFEB-mediated lysosomal biogenesis and autophagy play critical roles in promoting the pathogenesis of pancreatitis." (PMID 32349207, 2020). "Ongoing work is underway to investigate the mechanisms by which TFEB is inactivated during alcohol consumption, and hopefully to identify small molecules targeting TFEB for preventing/treating pancreatitis." (PMID 32349207, 2020). "In addition, food restriction determines the susceptibility of mouse model to coxsackievirus infection and pancreatitis by regulating TFEB and autophagy." (PMID 36793898, 2023). "Furthermore, mice with defective pancreatic lysosomal biogenesis by double deletion of TFE3 and acinar cell TFEB also develop spontaneous pancreatitis." (PMID 32349207, 2020). "Impairment of TFEB-mediated lysosomal biogenesis by alcohol may lead to insufficient autophagy and promote alcohol-induced pancreatitis." (PMID 31987928, 2020). "Decreased lysosome and nuclear TFEB staining were also observed in these pancreatitis samples." (PMID 31987928, 2020). "It is likely that impaired TFEB-mediated lysosomal biogenesis by alcohol consumption may prime these individuals to be more prone to develop pancreatitis in the presence of other insults such as smoking." (PMID 31987928, 2020). "While a high-fat diet has been associated to pancreatitis, a Western diet that contains more than 40% fat did not cause more injury in these acinar cell–specific Atg5 or TFEB KO mice (data not shown)." (PMID 31987928, 2020). "We recently reported that TFEB was impaired in caerulein-induced experimental pancreatitis in mice." (PMID 31987928, 2020). "Furthermore, the activation of TFEB by mTORC1 inhibitors has been shown to rescue a mouse model from lethal pancreatitis and chronic ethanol-induced liver injury; these effects were closely associated with the onset of sepsis or during sepsis and worsened clinical outcomes." (PMID 34899355, 2021). "TFEB-mediated lysosomal biogenesis mainly acts at the late stage of autophagy, we next wondered whether blocking the upstream autophagosome formation would also affect alcohol-induced pancreatitis." (PMID 31987928, 2020). "Hence, targeting TFEB-mediated lysosomal biogenesis may be a promising therapeutic approach to prevent and treat pancreatitis." (PMID 31987928, 2020). "Pancreatic acinar cell–specific depletion of ATG5 or TFEB in the mouse developed fibrotic pancreatitis regardless of alcohol feeding." (PMID 31987928, 2020). "Together, these data indicate that genetic deletion of Atg5 in acinar cells promotes the fibrotic pancreatitis after the mice were fed with the Lieber-Decarli liquid diet regardless of ethanol feeding, which is similar to TFEB KO mice." (PMID 31987928, 2020).
pancreatitis (continued). "More importantly, human pancreatitis tissues either from alcohol or non-alcohol etiology show decreased TFEB nuclear staining." (PMID 32349207, 2020).
proteinopathies (5 papers, 2019 to 2024). "To elucidate novel mechanisms contributing to proteinopathy in PD, we investigated the effect of GBA1 mutations on the transcription factor EB (TFEB), the master regulator of the autophagy-lysosomal pathway (ALP)." (PMID 37332877, 2023).
Sepsis (5 papers, 2021 to 2023). Sepsis is defined as life-threatening organ dysfunction caused by a dysregulated host response to infection. "Increasing shreds of evidence have linked TFEB and the Subsequent Lysosome biogenesis with pathogenetic mechanisms and control of sepsis." (PMID 38130644, 2023). "Except for ATG proteins involved in the regulation of autophagy, several diverse factors are involved in the regulation of autophagy-lysosome pathway, including TFEB and lysosome-associated proteins in sepsis." (PMID 38105228, 2023). "In summary, TFEB has been recognized as the pharmacological target of their potential in treating sepsis." (PMID 38130644, 2023). "TFEB-dependent xenophagy is critical for antimicrobial defense and is fundamental for the prevention and control of sepsis." (PMID 34899355, 2021). "Recently, increasing evidences have linked TFEB and the TFEB dependent ALP with pathogenetic mechanisms and therapeutic implications in sepsis." (PMID 34899355, 2021). "The TFEB dependent ALP is fundamental for organ protection in sepsis by reducing tissue inflammation, alleviating oxidative stress and controlling metabolic process." (PMID 34899355, 2021). "Therefore, time-dependent changes in the expression and activity of TFEB in sepsis are needed to be evaluated." (PMID 38130644, 2023). "Thus, our study suggested that Erbin alleviated sepsis-induced inflammatory responses and organ injuries by rescuing dysfunction of the autophagy-lysosomal pathway through TFEB-14-3-3 and TFEB-PPP3CB pathway." (PMID 38105228, 2023). "Both the status of autophagy and the activity of TFEB are altered during the progression of sepsis." (PMID 38130644, 2023). "This may offer an alternative strategy for eliminating pathogens during sepsis by modulating the activity of TFEB." (PMID 34899355, 2021). "Several recent studies have described pivotal immunomodulatory roles for TFEB activators in sepsis." (PMID 34899355, 2021). "The control of inflammation is another prominent effect of TFEB in sepsis." (PMID 34899355, 2021). "In this mini-review, we aim to summarize recent advances in the regulatory mechanisms associated with the TFEB- dependent ALP and discuss how the targeting of TFEB may provide us with pharmacological options for the intervention of sepsis." (PMID 34899355, 2021). "In addition, emerging evidence has associated TFEB and the TFEB-dependent ALP with pathogenic mechanisms in inflammatory diseases, including sepsis, thus creating the potential for the discovery of new therapeutic options." (PMID 34899355, 2021). "TFEB activators have also been demonstrated to confer organ protection in sepsis." (PMID 34899355, 2021). "In addition, TFEB activators with diversified pharmacological targets are summarized, along with recent advances of their potential therapeutic applications in treating sepsis." (PMID 34899355, 2021). "TFEB-dependent xenophagy and autophagylysosome pathway (ALP) is critical for antimicrobial defense and therapeutic applications of sepsis." (PMID 38130644, 2023). "By administering ZLN005 to the cecum perforation ligation (CPL) model of sepsis and analyzing intraperitoneal cells, ZLN005 was shown to be a transcription factor EB (TFEB) activator involved in lysosome biogenesis as well as a lysosomal acidifier." (PMID 37841276, 2023). "The TFEB-dependent ALP is widely regarded as a critical pathway that can control excessive inflammation and restore immune homeostasis during sepsis." (PMID 34899355, 2021). "Therefore, TFEB may inhibit inflammation in sepsis via several different mechanisms." (PMID 34899355, 2021). "Therefore, this review describes the existed knowledge about the mechanisms of TFEB activation in regulating the ALP and the evidences of their protection against sepsis, such as immune modulation and organ protection." (PMID 34899355, 2021).
Sepsis (continued). "We hypothesized that TFEB and SNAREs may play key roles in the modulation of A-L fusion by mTOR during sepsis, a possibility that has not been previously investigated." (PMID 35435531, 2022).
tuberculosis (5 papers, 2019 to 2023). A chronic, recurrent infection caused by the bacterium Mycobacterium tuberculosis. "A role for TFEB in the anti-tubercular activity of statins, as demonstrated in the present work, implies that TFEB may be classified as a target for anti-tuberculosis therapeutic intervention." (PMID 32848049, 2020). "Therefore, the TFEB-induced autophagy regulatory mechanisms that are cross-intervened during infection and starvation might be developed as potential HDTs to combat tuberculosis." (PMID 38138088, 2023).
acute myeloid leukemia (4 papers, 2021 to 2024). Acute myeloid leukemia (AML) is a group of neoplasms arising from precursor cells committed to the myeloid cell-line differentiation. "In acute myeloid leukemia, Myc directly inhibits the expression of TFEB (a transcription factor regulated by mTORC1) and regulates DNA methylation and cell differentiation." (PMID 36506508, 2022). "Reflecting the highly contextual role of autophagy in cancer, while TFEB and related factors have frequently been regarded as oncogenes, TFEB can behave as a tumor suppressor, as recently reported for acute myeloid leukemia (AML)." (PMID 34685734, 2021). "This interaction is particularly significant as TFEB acts as a tumor suppressor in acute myeloid leukaemia by promoting myeloid differentiation and cell death, thereby emphasising the critical nature of the CD38–MYC relationship and introducing additional complexity." (PMID 39364393, 2024). "TFEB is the primary regulator of the autophagy–lysosomal pathway and plays a role in suppressing cancer in acute myeloid leukemia and induces differentiation and death of acute myeloid leukemia cells." (PMID 37342196, 2023).
breast tumor (4 papers, 2020 to 2025). "In the breast tumor microenvironment (TME), macrophage-specific TFEB knockout promoted breast tumor growth by inducing macrophage M2 polarization through autophagy/lysosome-mediated pathways." (PMID 33732651, 2021).
Cerebral ischemia (4 papers, 2021 to 2025). Restriction of arterial blood supply to the brain associated with insufficient oxygenation to support the metabolic requirements of the tissue. "In this study, we showed that melatonin promotes TFEB nuclear translocation in a cerebral ischemia model, enhancing autophagy and reducing neuronal death." (PMID 39940940, 2025). "Recently, PF11 was shown to significantly alleviate autophagy flux defects in a cerebral ischemia injury model by increasing the nuclear translocation of TFEB." (PMID 33995096, 2021). "TFEB emerges as a promising target for neuroprotective therapy in cerebral ischemia." (PMID 39940940, 2025). "Indeed, some publications have reported that TFEB activators and GSK-3β inhibition facilitated TFEB nuclear translocation and thus conferred neuroprotection at 24 h after cerebral ischemia/reperfusion injury." (PMID 37601043, 2023). "Following cerebral ischemia onset, the balance between mitochondrial fission and fusion is disrupted, and TFEB activity is altered; therefore, it is reasonable to speculate that TFEB is involved in maintaining the balance between mitochondrial fission and fusion." (PMID 37491856, 2024).
chronic kidney disease (4 papers, 2018 to 2025). Impairment of the renal function secondary to chronic kidney damage persisting for three or more months. "Finally, higher body mass index was associated with increased vacuolation and decreased nuclear TFEB in the proximal tubules of patients with chronic kidney disease." (PMID 36649084, 2023). "In patients with chronic kidney disease (CKD), a higher body mass index has been linked to increased vacuolation and decreased nuclear TFEB levels in proximal tubules, indicating autophagy dysregulation." (PMID 40366502, 2025). "Finally, we evaluated vacuole formation and TFEB activity in the tubules of nonobese and obese patients with chronic kidney disease (CKD)." (PMID 36649084, 2023).
COVID-19 (4 papers, 2020 to 2025). A disease caused by infection with severe acute respiratory syndrome coronavirus 2. "This mini review synthesizes current knowledge on the TFEB-ALP axis in COVID-19 pathogenesis, highlighting its influence on acute immunopathology and its potential contribution to post-acute sequelae (Long COVID)." (PMID 41394849, 2025). "This mini review synthesizes current insights into the viral manipulation of ALP and the immunological role of TFEB in COVID-19." (PMID 41394849, 2025). "Thus, TFEB functions at a critical intersection of antiviral defense, cellular stress adaptation, and immune regulation, making it a promising target for therapeutic modulation in COVID-19." (PMID 41394849, 2025). "Hence, to investigate the potential roles of TLR4/TFEB in M. pneumoniae infection may provide a potential strategy for COVID-19." (PMID 35965629, 2022). "In addition, TFEB’s role in cytokine regulation and inflammasome clearance suggests that its activation might mitigate hyperinflammation and cytokine storm, both of which are drivers of severe COVID-19." (PMID 41394849, 2025).
ischemic stroke (4 papers, 2021 to 2025). A stroke disorder caused by obstruction of blood flow to the brain, due to thrombotic (local blood clot formation) or embolic (due to a blood clot or other material traveling from another site) event. "We then describe the regulatory mechanisms underlying the transcriptional activity of TFEB as well as its sensing and regulation of energy metabolism following ischemic stroke." (PMID 37491856, 2024). "Additionally, we explore the effects of TFEB on the various pathological processes underlying ischemic stroke and current therapeutic approaches." (PMID 37491856, 2024). "Taken together, the research results on the regulatory mechanisms of TFEB sufficiently demonstrate that it is a good therapeutic target for ischemic stroke treatment." (PMID 37491856, 2024). "This article describes the basic structure, regulation of transcriptional activity, and biological roles of TFEB relevant to ischemic stroke." (PMID 37491856, 2024). "Future studies should evaluate the actions of TFEB in NVUs in ischemic stroke; moreover, reliable clinical studies are warranted to validate and further explore the function of TFEB in human-derived cells." (PMID 37491856, 2024). "Next, we summarize the mechanisms of action of TFEB in the various pathological processes of ischemic stroke, its role in the neurovascular unit, and the current therapeutic approaches." (PMID 37491856, 2024). "Conversely, under nutrient-deprived conditions following ischemic stroke, the nucleotide states of the Rags are altered so that they cannot bind to mTORC1 or TFEB." (PMID 37491856, 2024). "This study preliminarily elucidated the neuroprotective mechanism of MEL to enhance autophagy flux by induction of TFEB nuclear translocation in neurons after ischemic stroke." (PMID 34575099, 2021). "We, therefore, concluded that melibiose-elicited neuroprotection was exerted by ameliorating autophagy flux via facilitation of TFEB nuclear translocation in neurons after ischemic stroke." (PMID 34575099, 2021). "This suggested that MEL possessed the pharmacological efficacy to facilitate TFEB nuclear translocation after ischemic stroke." (PMID 34575099, 2021). "We have only recently begun to understand the contribution of TFEB to ischemic stroke." (PMID 37491856, 2024). "The information compiled here may inform clinical and basic studies on TFEB, which may be an effective therapeutic drug target for ischemic stroke." (PMID 37491856, 2024). "Given the broad functions of TFEB, elucidating the TFEB-mediated transcriptional network and investigating TFEB-targeting drugs may advance ischemic stroke treatment." (PMID 37491856, 2024). "Although TFEB plays a neuroprotective role, its potential effect on ischemic stroke remains unclear." (PMID 37491856, 2024). "Therefore, metabolic dysfunction is a potential target for ischemic stroke treatment, and TFEB is an emerging metabolic regulator that can reprogram glucose and lipid metabolism." (PMID 37491856, 2024). "Emerging evidence suggests that TFEB may be a promising therapeutic target for some brain diseases, such as AD and ischemic stroke." (PMID 37143104, 2023). "We, therefore, discussed whether MEL could also elicit a neuroprotection against ischemic stroke by boosting TFEB nuclear translocation." (PMID 34575099, 2021). "Our data suggests that melibiose-augmented neuroprotection may be achieved by ameliorating autophagy flux via facilitation of TFEB nuclear translocation in neurons after ischemic stroke." (PMID 34575099, 2021). "Furthermore, electroacupuncture significantly enhances TFEB activity and improves ALP function in the brain, which indicates that it may ameliorate ischemic stroke via TFEB signaling." (PMID 37491856, 2024). "Therefore, TFEB may be a potential target for improving motor rehabilitation in ischemic stroke." (PMID 37491856, 2024).
ischemic stroke (continued). "Pharmacotherapy and physiotherapy are currently the main treatment strategies for ischemic stroke and may exert their AIS neuroprotective effects through TFEB signaling." (PMID 37491856, 2024).
multiple myeloma (4 papers, 2017 to 2025). "Bortezomib and siramesine can synergistically inhibit the growth of multiple myeloma cells, which is related to the increased autophagy expression in multiple myeloma cell lines and the expression of TFEB with nuclear translocation is also enhanced." (PMID 34218584, 2021).
osteoarthritis (4 papers, 2018 to 2023). A noninflammatory degenerative joint disease occurring chiefly in older persons, characterized by degeneration of the articular cartilage, hypertrophy of bone at the margins and changes in the synovial membrane. "Studies have shown that TFEB mediated autophagy can delay chondrocyte senescence and thus delay the progression of osteoarthritis." (PMID 37679844, 2023). "Therefore, for the first time, we introduced Ajugol into OA (osteoarthritis) research and discovered its ability to activate TFEB-mediated autophagy, thereby alleviating ER stress." (PMID 37679844, 2023).
osteosarcoma (4 papers, 2019 to 2025). A usually aggressive malignant bone-forming mesenchymal neoplasm, predominantly affecting adolescents and young adults. "In line with this, inhibition of TFEB-mediated lysosomal degradation of ferritin by a TFEB inhibitor suppressed ferroptosis in osteosarcoma cells." (PMID 40083935, 2025). "It has also been shown that TFEB is activated, translocated to the nucleus and mediates osteosarcoma cells death via increasing autophagy-related gene in response to arsenic trioxide toxicity." (PMID 31413743, 2019).
PEComas (4 papers, 2021 to 2025). "Explaining the mutual exclusivity between TSC1/2 inactivation and MiT/TFE gene rearrangements in PEComas, we and others have previously shown that mTORC1 activation leads to constitutive activation of TFEB and TFE3 through FLCN inactivation." (PMID 41044182, 2025). "Both TFE3 and TFEB tRCCs may overlap with each other’s and with other RCCs’ morphologies, in particular with clear cell RCC, papillary RCC or, more rarely, clear cell papillary renal cell carcinomas as well as perivascular epithelioid cell tumors (PEComas)." (PMID 35886994, 2022).